GFAP (glial fibrillary acidic protein)
Diseases named in the same sentence as GFAP in open-access papers (continued):
Sharing a sentence is not in itself a finding about the gene and the disease.
neurodegenerative disease (continued). "High levels of blood GFAP can be found in individuals with other neurodegenerative diseases, but this finding occurs at the symptomatic, and thus advanced, stages of the disease." (PMID 34661615, 2021). "GFAP is an intermediate filament protein found in astrocytes of central nervous system and a marker of reactive astrocytes seen in neurodegenerative disease and in TBI." (PMID 34899299, 2021). "Biomarkers that track astrocyte biology, such as GFAP, have been investigated over the past few years in neurodegenerative diseases." (PMID 34893073, 2021). "During neurodegenerative disease, astrocytes become reactive and gain abnormal roles that include enhanced GFAP expression." (PMID 35126292, 2021). "Upregulation of inflammatory A1-type astrocyte exosomes, glial fibrillary acidic protein- (GFAP-) positive, plays an essential role in human inflammatory and neurodegenerative diseases of the CNS." (PMID 34976232, 2021). "CSF GFAP was also increased in other neurodegenerative diseases such as Lewy body dementias, Parkinson’s disease, frontotemporal dementia, prion disease, and Creutzfeldt-Jakob’s disease." (PMID 33578866, 2021). "GFAP is extremely sensitive to changes in the homeostasis of the brain and responds early in the course of neurodegenerative disease." (PMID 32049030, 2020). "Reactive astrogliosis, routinely observed immunohistochemically as an increase in GFAP signal, is one of the central features of prion and other neurodegenerative diseases." (PMID 31649496, 2019). "Reactive astrogliosis, routinely observed immunohistochemically as an increase in glial fibrillary acidic protein (GFAP) signal, is a well-documented feature of chronic neuroinflammation associated with neurodegenerative diseases." (PMID 31649496, 2019). "Brain degeneration was manifested by the loss of DARPP32-positive cells, activated microglia, increased level of GFAP and demyelination." (PMID 31704691, 2019). "Cytokines, including TNF-α and IL-1β, have been shown to mediate reactive astrogliosis, which is reflected by the expression of glial fibrillary acidic protein (GFAP) and cell migration, in neurodegenerative diseases." (PMID 31185608, 2019). "Ceftriaxone has been found to interact with GFAP, one of the proteins involved in specific neurodegenerative diseases, inhibiting their pathological aggregation." (PMID 30065161, 2018). "As we already described in the Introduction above, a number of previous studies support that GFAP is correlated to specific conditions in patients with various neurodegenerative diseases." (PMID 30487774, 2018). "In neurodegenerative diseases, reactive gliosis or astrocytosis and enhanced glial fibrillary acidic protein (GFAP) expression are occurring in concert with neuronal degeneration." (PMID 28883901, 2017). "S100B is a multifunctional protein that, like GFAP, is relatively restricted to astrocytes and has served as a marker for brain damage in neurodegenerative diseases." (PMID 25166759, 2014). "Increased expression of GFAP represents astroglial activation and gliosis in many neurodegenerative diseases; therefore, GFAP has been used as an indicator of brain injury." (PMID 24156724, 2013). "Reactive gliosis in the retina and in the brain is observed in neurodegenerative diseases, CNS lesions and during aging and can be visualize by GFAP immunoreactivity." (PMID 22384090, 2012). "Better characterisation of the GFAP isoforms is highly important for CNS research, to gain more insight in the modulation of astrocyte function under normal homeostatic conditions or neurodegenerative disease." (PMID 22479412, 2012). "Immunostaining with the purified GFAP+1 antibody revealed conspicuous astrocytes in numerous areas of the CNS in older control donors (>50 years) or donors with neurodegenerative diseases." (PMID 19888461, 2009).
neurodegenerative disease (continued). "Additionally, evaluating the impact of PTMs on GFAP biomarker detection in clinical assays is necessary to enhance the reliability and accuracy of GFAP-based diagnostics for neurodegenerative diseases." (PMID 40690136, 2025). "However, prior studies on serum GFAP in persons with neurodegenerative diseases uniformly reported elevated levels." (PMID 40192786, 2025). "Our next objective was to investigate if TT1Ct could counteract brain degeneration and interfere TrkB-T1/GFAP expression when excitotoxicity occurs in vivo." (PMID 40225562, 2025). "The limited contribution of GFAP to group differentiation was notable given its recognized role in AD as a marker of astroglial activation and early neuroinflammation, processes common to many neurodegenerative diseases." (PMID 40314736, 2025). "A focused proteomic analysis of GFAP isoforms in neurodegenerative diseases could aid in understanding the role of these different isoforms per disease and potentially pinpoint discovering disease‐specific GFAP isoforms to develop into novel biomarkers." (PMID 39289040, 2025). "Based on emerging evidence demonstrating increased GFAP concentrations in biofluids from individuals with neurodegenerative diseases, we evaluated whether plasma or CSF GFAP is elevated in SCA7 patients compared to the controls." (PMID 40507882, 2025). "Under pathological conditions, for example, neurodegenerative diseases, astrocyte activation, as reflected by increased GFAP and S100β levels, could lead to increased production of inflammatory mediators associated with BBB disruption." (PMID 41221374, 2025). "While GFAP has been associated with other neurodegenerative diseases, it has not been investigated as a biomarker for SCA7." (PMID 40507882, 2025). "Moreover, the specificity of GFAP for AD needs further evaluation, as elevated plasma levels have been observed in various neurodegenerative diseases." (PMID 40690136, 2025). "Glial fibrillary acidic protein (GFAP), a key astrocytic cytoskeletal component, is released into the cerebrospinal fluid (CSF) during neuroinflammation and serves as a well-established marker of neurodegenerative diseases, including AD." (PMID 40458441, 2025). "Given the link between GFAP levels and neurodegenerative diseases, it is plausible that these cells may also play a role in disease pathology under specific conditions." (PMID 41221125, 2025). "Therefore, increased levels of both blood GFAP and NfL can be detected during neurodegenerative diseases such as AD, which is consistent with the findings of this study." (PMID 38352136, 2024). "GFAP expressions are significantly elevated in neurodegenerative diseases, including AD and PD." (PMID 39576344, 2024). "Indeed, postmortem brains from human neurodegenerative diseases, including PD, exhibit A1 astrocytes expressing Glial Fibrillary Acidic Protein (GFAP+)." (PMID 39281666, 2024). "Finally, future studies should consider the utility of GFAP in other neurological conditions, such as neurodegenerative diseases and psychiatric disorders, to expand its applications beyond TBI." (PMID 39796043, 2024). "However, it is important to mention that elevated levels of GFAP have been reported consistently in other neurodegenerative diseases." (PMID 38940331, 2024). "The lack of an increase in GFAP in the absence of TYROBP led us to specifically interrogate other astrocytic markers often associated with neurodegenerative disease and neuroinflammation, i.e., “neurotoxic reactive astrocytes”." (PMID 38459557, 2024). "GFAP, NfL, and p‐tau181 are valuable predictors of cognition and function across common neurodegenerative diseases, and may be useful in specialized clinics and clinical trials." (PMID 38105605, 2024). "GFAP provides insight into the inflammatory and glial responses associated with neurodegenerative diseases and is elevated in several neurodegenerative and non-neurodegenerative neurological diseases." (PMID 39242539, 2024).
neurodegenerative disease (continued). "Suppressing the hyperactivation of microglia and astrocytes is an essential factor for slowing the progression of neurodegenerative diseases; thus, lower brain GFAP and CD36 concentrations may indicate suppressed neuroinflammation." (PMID 39619979, 2024). "Numerous studies have demonstrated higher levels of blood GFAP in AD patients compared to other neurodegenerative diseases due to variations in neuroinflammation heterogeneity or different types/patterns of astrocyte hyperplasia observed across various neurodegenerative conditions." (PMID 38352136, 2024). "Glial fibrillary acidic protein (GFAP): astrogliosis, i.e., the inflammatory reaction against damage that characterises glial cells in various neuropathological contexts, including neurodegenerative diseases, can be assessed by measuring related markers, such as GFAP." (PMID 37511491, 2023). "Upregulation of GFAP protein and mRNA is a feature of reactive astrocytes that undergo morphological, molecular and functional changes in their response to injury and in response to a variety to neuroinflammatory and neurodegenerative disease." (PMID 35930103, 2023). "However, under pathological conditions, increased GFAP expression reflects astrocyte activation and is believed to be a pivotal contributor to the pathogenesis of neurodegenerative diseases, such as AD and PD." (PMID 37475029, 2023). "Additionally, since GFAP, NfL and tau proteins are presently being used as biomarkers in neurodegenerative diseases, there is also a need to distinguish neuro-PASC from early neurodegenerative processes." (PMID 37545721, 2023). "In addition, plasma neurofilament light chain (NfL), a marker of axonal damage, increases in various neurodegenerative diseases, and plasma glial fibrillary acidic protein (GFAP) is a marker of reactive astrogliosis and is elevated in the early stages of AD." (PMID 37480401, 2023). "Therefore, GFAP and Iba-1 are also reliable biomarkers for brain damage in the context of neurodegenerative diseases." (PMID 37048114, 2023). "Interestingly, these significantly correlated with GFAP, which is proposed to reflect neuroinflammation in the early stages of neurodegenerative disease." (PMID 38239488, 2023). "Thus, GFAP serves as a biomarker of neurodegenerative diseases, including AD, dementia with Lewy bodies, and frontotemporal dementia." (PMID 37829140, 2023). "In addition, we also identified neurodegenerative disease- and cancer-associated pathways in the network, suggesting a possible transcriptional similarity between TSK deficient GFAP+ cells and cells of these diseases." (PMID 36478736, 2022). "GFAP level is positively related to the progression of neurodegenerative diseases." (PMID 35655596, 2022). "These consisted of markers of astrocytic and microglial activation (GFAP, vimentin, galectin-1, and clusterin) and indicators of neurodegenerative disease (ApoE and serpinA3N) that each demonstrated significant prion effects and PAM effects from the MS proteomic analysis." (PMID 36378750, 2022). "However, it also needs to be mentioned that the “minimum survival time” determination based on supratentorial immunopositivity for GFAP in neurons can be biased, if the deceased suffered from neurodegenerative diseases." (PMID 34114049, 2021). "As astrogliosis occurs in various scenarios of neurodegenerative diseases, the up-regulation of GFAP expression correlate well with the proliferation of astrocytes (10, –12), implying that GFAP might boost the expansion of astrocytes population." (PMID 33753498, 2021). "Decrease of GFAP expression may also be in favor of the exercise group, due to it being also a marker of inflammatory processes, glial scars, neurodegenerative diseases, and aging." (PMID 33996841, 2021).
neurodegenerative disease (continued). "Neuronal loss in central nervous system (CNS) acute injuries and chronic neurodegenerative diseases is invariably accompanied by an astrocyte reaction, which has been traditionally depicted by an increased glial fibrillary acidic protein (GFAP) immunoreactivity." (PMID 32736565, 2020). "Moreover, GFAP expression increases in central nervous system injury, neurodegenerative disease, and aging." (PMID 32257907, 2019). "In addition, GFAP in astrocytes has been described as an index of reactive astrogliosis, a complex phenomenon closely related to neuronal damage seen in neurodegenerative diseases and other brain injuries." (PMID 32082134, 2019). "The use of β-lactam antibiotic ceftriaxone as a potential drug to ameliorate neurodegenerative diseases was studied using GFAP and lysozyme showing that the presence of ceftriaxone could reduce significantly the rate of UV photodenaturation of the proteins." (PMID 30065161, 2018). "Upon activation, astrocytes undergo a morphological transformation typified by increased intermediate filament expression (i.e., glial fibrillary acidic protein (GFAP) and vimentin) and reactive astrocytes have been implicated in the pathogenesis of various neurodegenerative diseases." (PMID 26578874, 2015). "Moreover it has been demonstrated that several neurodegenerative diseases elicit the reactive Müller cell gliosis with a rapid and massive GFAP accumulation." (PMID 21799881, 2011). "In conclusion, conditional BDNF delivery regulated by the GFAP promoter in astrocytes could well be a therapeutic strategy for treatment of HD and other neurodegenerative diseases." (PMID 21985529, 2011). "While GFAP release into the bloodstream is well-documented in acute brain injuries with transient blood-brain barrier disruptions, the mechanisms behind increased blood GFAP levels in neurodegenerative disease progression—especially when blood-brain barrier integrity is maintained—remain elusive." (PMID 40346659, 2025). "This difference in the time course of GFAP in acute compared to chronic events may be a reflection of the molecular and functional astrocytic changes in response to acute neuronal injury compared to chronic neurodegenerative disease pathology." (PMID 39289040, 2025). "The significance of cerebral GFAP and S100B levels should be discussed according to the context; here, considering situations involved with brain damage, all of the compounds tested showed a similar profile, suggesting astrocytic dysfunction, as found in neurodegenerative diseases." (PMID 38535311, 2024). "As the field of CSF diagnostics evolves, other biomarkers are being evaluated that may offer further insights into neurodegenerative diseases, including neurofilament light chain (NfL), a marker of neuronal injury, and glial fibrillary acidic protein (GFAP), a marker of astrocyte activation." (PMID 39703457, 2024). "Therefore, increased GFAP expression in neurons seems common to many neurodegenerative diseases." (PMID 35960762, 2022). "Furthermore, GFAP can enter the blood circulation from the brain through the blood-brain barrier, so the changes in protein levels of GFAP in the central nervous system and peripheral blood can reflect the degree of astrocyte damage in neurodegenerative diseases." (PMID 33192662, 2020). "These pathways were, in general, shared across all neurodegenerative diseases, even though the major overlap was found for the synaptic functions (BDNF, CCL2, ACHE, GFAP, NEFH or NEFL) and microglia pathways (TREM2, IL13, IL6R IFNG)." (PMID 41250190, 2025). "Measurement of plasma GFAP and 11C‐DED binding in the context of other neurodegenerative diseases can help elucidate the relationship between these measures, functional astrocytic changes and other types of neuropathology." (PMID 39289040, 2025).
neurodegenerative disease (continued). "Recently, blood glial fibrillary acidic protein (GFAP), an astrocytic intermediate filament, has been shown to be elevated in various neuroinflammatory and neurodegenerative diseases." (PMID 40518460, 2025). "For instance, studies in ALS mouse models have demonstrated that rTMS can induce transcription of glial fibrillary acidic protein (GFAP), a marker of astrocyte activation that is dysregulated in ALS and other neurodegenerative diseases." (PMID 41011076, 2025). "In AD, plasma GFAP rises early in the preclinical phase, whereas in FTD and other neurodegenerative diseases, it increases during symptomatic stages." (PMID 40305176, 2025). "Astrocyte activation, marked by the overexpression of GFAP and S100β, can mediate inflammation and contribute to BBB disruption in neurodegenerative diseases (e.g., AD)." (PMID 41221374, 2025). "Astrocytes activation, marked by the up-regulation of glial fibrillary acidic protein (GFAP), presents in some pathological conditions including neurodegenerative diseases." (PMID 37349834, 2023). "Interestingly, we found a greater number of BST2, HLA-E, PD-L1, and PDPN positive GFAP+ astrocytes in AD post-mortem brains compared to brains from non-symptomatic individuals, warranting further investigations on the roles that these markers play in neurodegenerative disease." (PMID 35592112, 2022). "The increased expression of GFAP has been detected in most CNS pathologies, such as TBI, ischemia, and neurodegenerative diseases." (PMID 36233034, 2022). "Therefore, elevations in circulating GFAP are unlikely to be a specific marker for incident AD but may rather broadly indicate increased risk for neurodegenerative disease regardless of etiological cause." (PMID 36056631, 2022). "Glial fibrillary acidic protein (GFAP) is expressed in the cytoskeleton of astrocytes and has been found significantly increased in CSF in AD and other neurodegenerative diseases compared to healthy controls." (PMID 33773595, 2021). "Previous studies have reported a weak correlation between CSF GFAP and YKL-40 levels in neurodegenerative diseases." (PMID 34893073, 2021). "Thus, we aimed to evaluate the utility of GFAP and NfL levels as biomarkers for SCA7, building on their established roles in other neurodegenerative diseases." (PMID 40507882, 2025). "Additionally, plasma glial fibrillary acidic protein (GFAP) and neurofilament light chain (NfL) have emerged as potential biomarkers for AD and other neurodegenerative diseases, further expanding the potential of blood‐based diagnostics." (PMID 40613333, 2025). "During astrogliosis, GFAP is released into biofluids, making it a candidate for non-invasive diagnosis and tracking of neurodegenerative diseases." (PMID 39554381, 2024). "For instance, levels of neurodegenerative biomarkers such as total tau, p-tau181, glial fibrillary acidic protein (GFAP), and neurofilament light (NfL) were increased following COVID-19 infection in patients without a history of neurodegenerative disease." (PMID 39839305, 2024). "As such, our broad results are in keeping with the idea that GFAP and NfL are not specific to a single neurodegenerative disease process, and support some neuropathological overlap across these diseases, especially in AD/MCI and PD." (PMID 38105605, 2024). "It should be emphasized that the GFAP change is not specific for AD but for many neurodegenerative diseases." (PMID 37829140, 2023). "First, plasma GFAP levels were not higher among individuals with non-AD neurodegenerative diseases in the TRIAD and Paris cohorts." (PMID 34661615, 2021). "Hindering GFAP palmitoylation rescue both astrogliosis and neurodegenerative pathology in PPT1-KI mice and hereby offer palm-C291 in GFAP as a possible pharmaceutical target for curing INCL and other possible neurodegenerative diseases." (PMID 33753498, 2021).